LEP (leptin)
Diseases named in the same sentence as LEP in open-access papers (continued):
Sharing a sentence is not in itself a finding about the gene and the disease.
Obesity (continued). "The device has been developed to quantify the gut hormone leptin, an essential protein for the regulation of energy balance, with links to metabolic conditions such as obesity and type 2 diabetes." (PMID 35884340, 2022). "Leptin is a well-established obesity marker that plays a major role in regulating immunity, appetite, and energy homeostasis." (PMID 35955698, 2022). "The increased leptin signaling characteristic of obesity increases PD-1 expression in T cells, resulting in T cell exhaustion and contributing to heightened inflammation." (PMID 35752704, 2022). "In people with obesity, leptin values are generally higher (mainly due to increased adipocytes and leptin resistance), and the profile shows a peak at 02:00." (PMID 35407646, 2022). "Adipokines are a large family of cytokines including adiponectin, leptin, and resistin, which are generated and released by adipocytes and are involved in obesity and insulin resistance." (PMID 36012327, 2022). "For postmenopausal women, obesity-induced increases in leptin levels induce endothelial dysfunction and hypertension through sympathetic activation, which is one of the non-negligible triggers for the occurrence of cardiovascular accidents in women." (PMID 36012601, 2022). "On the other hand, according to recent research, CAV1 expression is increased in human obesity, suggesting that leptin can play a crucial role." (PMID 36151575, 2022). "Pro-inflammatory cytokines increase leptin synthesis and release, contributing to chronic inflammation in obesity." (PMID 36499312, 2022). "Both leptin and adiponectin constitute major adipokines produced by the adipose tissue and are inversely regulated in obesity." (PMID 35624723, 2022). "In correlation with obesity, the modulated leptin signaling was a factor for PC that promoted cell proliferation by activating STAT3 and PI3K/Akt signals." (PMID 37529006, 2022). "Leptin, a cytokine-like peptide hormone secreted by white adipose tissue, has long been stipulated to connect obesity with OA." (PMID 35873487, 2022). "Leptin is an adipokine that is released by both maternal adipose tissue and the placenta and its role as a biomarker of obesity has been well studied." (PMID 36005607, 2022). "For example, plasma resistin levels are positively correlated to obesity and IR in mice, and resistin neutralization using the leptin antibody improved IR in mice." (PMID 35740864, 2022). "While the leptin level increases in obesity, the adiponectin level decreases, and it has been found that this altered leptin/adiponectin ratio correlates with cancer aggressiveness." (PMID 35207557, 2022). "On the other side, metabolic factors are affected by obesity, e.g., the proliferation of chondrocytes, which is impaired in overweight individuals, or leptin secretion, a hormone regulating the food intake habits that was shown to also play a role in OA." (PMID 36676651, 2022). "The intrinsic leptin resistance in DIO rats is already present before the development of overt obesity." (PMID 35456307, 2022). "The association of leptin signaling and genetic variation with obesity and CRC is well known, but the genetic component of obesity and CRC is still in focus, whereby mutation gain is a crucial factor enabling the genetic process of CRC." (PMID 35563103, 2022). "Among the obesity-related markers, ghrelin (p = 0.031) and leptin (p = 0.017), known for their role in appetite regulation, showed significant changes due to the study oils effect." (PMID 36235579, 2022). "The possible mechanisms of obesity-driven metastasis include increased local and circulating proinflammatory cytokines, upregulated levels of adiponectin and leptin, reprogramming of cellular energetics, insulin resistance, and immune dysfunction." (PMID 36397145, 2022). "All of these studies showed the great importance of leptin in the relationship between obesity and osteoarthritis, and further research is needed to clarify the potential mechanism." (PMID 36615120, 2022).
Obesity (continued). "Among the hormones released, leptin levels were shown to be directly proportional to obesity and body fat levels." (PMID 35054972, 2022). "GDM was associated with subclinical inflammation, and affected women showed increased plasma leptin and lower plasma adiponectin levels independently of the degree of insulin sensitivity or obesity." (PMID 36432399, 2022). "Regarding the relationship of obesity with CRC, LEP polymorphisms such as rs7799039 and LEPR rs1137101 were shown to be associated with CRC risk, with specific alleles or genotypes linked to increased obesity risk." (PMID 35563103, 2022). "Of note, using an obesity mouse model, withaferin A was shown to represent a potent leptin sensitizer." (PMID 36012322, 2022). "Accordingly, abnormal circulating levels of TNF-α, IL-6, C-reactive protein (CRP) and leptin have been found in individuals with obesity, reflecting their overexpression in adipose tissue." (PMID 35565781, 2022). "The role of leptin and the leptin receptor gene in human obesity is now emerging but not well understood." (PMID 36232301, 2022). "Previously, it has been reported that the genetic variants in ADIPOQ, CETP, FTO, LEP, and LEPR genes are strongly correlated with obesity and associated metabolic complications in different ethnicities of the world." (PMID 36126070, 2022). "Regarding contractility effects, we found that leptin was effective only at a high concentration of 60 nM, which is related to severe obesity." (PMID 35955485, 2022). "Leptin is a peptide hormone secreted by adipose tissue and is an important determinant of obesity and its complications." (PMID 35941672, 2022). "Compared with children with normal weight and asthma, leptin and IL-10 were significantly higher in all the obese children, indirectly excluding a role of these cytokines, in particular leptin, for the asthma–obesity phenotype." (PMID 36291398, 2022). "The objective of the present study was to explore the relationships between several biomarkers crucially involved in obesity (ghrelin, insulin resistance, and leptin/adiponectin ratio) and eating styles in children and adolescents with obesity." (PMID 35057485, 2022). "Insulin resistance (IR) and leptin levels increase in hypothyroid children and adolescent; more with obesity." (PMID 35501770, 2022). "During obesity, the accumulation of elevated fat stores triggers a global, and permanent, inflammatory status that eventually leads to insulin and leptin resistance, paving the way to obesity-related co-morbidities." (PMID 36507349, 2022). "We calculated the proportion of total obesity effect mediated by leptin, fasting insulin, and ISI for disorders where the effects of obesity traits and mediators were significant at unadjusted P < 0.05." (PMID 35104295, 2022). "Our findings are in agreement with other studies that suggest a protective role of the peripherally restricted CB1 inverse agonist in obesity by reducing appetite, body weight, and leptin resistance." (PMID 36293486, 2022). "In our case-series, the children with CPP developed CPP before they became overweight or obese, which contradicts it being a result of obesity, estrogen or leptin." (PMID 35464054, 2022). "Obesity seems to affect the kidneys via the endocrine activity of the adipose tissue, with increased production of adipokines, such as leptin." (PMID 36289903, 2022). "The aim of this study includes molecular pathway and network analysis by using a systems pharmacology approach to identify a potential therapeutic mechanism of melatonin on leptin resistance-induced obesity." (PMID 35937803, 2022). "Research in obesity and diabetic mouse models has demonstrated that leptin and serum levels of FFAs play an essential role in regulating UCP3 expression in skeletal muscle, and that muscle thermogenesis in these models is impaired." (PMID 35323702, 2022). "Celastrol as a leptin sensitizer exhibited significant weight loss and food consumption reduction in HFD-obesity animals." (PMID 35444532, 2022).
Obesity (continued). "The lncRNA dysregulation led to the reduction of leptin, which undermined the afferent signal in the negative feedback loop associated with the maintenance of adipose tissue mass homeostasis, thus resulting in the leptin responsive-obesity." (PMID 36339448, 2022). "This validates the role of genetic variation in candidate genes in obesity, including leptin, thus motivating the interest in genetic variations in LEP and its receptor." (PMID 35563103, 2022). "In our study, adiponectin was inversely related to CRP in obesity, but, surprisingly, leptin was inversely related to CRP in normal-weight patients." (PMID 36428528, 2022). "In a patient-derived xenograft model of TNBC, leptin produced by obesity-altered adipose stem cells drove a prometastatic phenotype via upregulation of EMT-associated genes." (PMID 35752704, 2022). "A recent systematic review has shown that bariatric surgery leads to reduced leptin and increased adiponectin in adults with severe obesity." (PMID 35662920, 2022). "Evidence on the subject has found that in POMC neurons, overexpression of the unfolded protein response transcription factor (Xbp1s) decreases the expression of PTP1B and SOCS3, improves leptin and insulin sensitivity, and protects against obesity." (PMID 35563589, 2022). "Although the thesis concerning the increase in TSH in obesity due to the increased production of pro-TRH through the stimulation of the hypothalamus by leptin is plausible, there are certainly other mechanisms that influence (modulate) this relationship." (PMID 35399935, 2022). "Leptin is produced by adipocytes in proportion to fat stores, and thus represents a possible link between obesity and cancer." (PMID 35158824, 2022). "Diet-mediated PTPN1B regulation and the development of leptin resistance has been explored using mouse models of diet-induced obesity." (PMID 36295527, 2022). "The developed hyperinsulinemia and insulin resistance is a condition accompanying obesity that was attributed to various factors, including free fatty acids, leptin, cytokines, and androgens." (PMID 35972578, 2022). "As mentioned, leptin has a “providing” role in the use of energy in the immune system, and this role is impaired in obesity." (PMID 35406000, 2022). "Obesity-related pro-inflammatory adipokines, such as leptin, interleukin 6 and tumor necrosis factor a, inhibit normal insulin signaling, leading to insulin resistance and promoting endometrial proliferation." (PMID 35615721, 2022). "Leptin is a hormone derived from adipocytes that is secreted in proportion to the amount of adipocytes in the body, with high circulating plasma levels in obesity and low circulating plasma levels in states of starvation." (PMID 36097042, 2022). "Ultimately, increased circulating levels of leptin during obesity will culminate with the dysruption of the signalling pathway in an organ specific manner." (PMID 36855701, 2022). "Certain studies have also concluded that adipokines such as resistin, leptin, and adiponectin have adverse effects on coronary arteriolar dilation in obesity which in turn is related to the development of coronary artery disease." (PMID 36299943, 2022). "Knowledge regarding changes in the biosynthesis of leptin, visfatin and chemerin in obesity is primarily based on research evaluating theirs levels in the patient’s serum or adipose tissue." (PMID 35549673, 2022). "SNP rs28954114 (+328G/A) in the 3′-UTR of LEP was observed in one subject with obesity and two control subjects in heterozygous condition." (PMID 36619235, 2022). "Recently, AGRP neurons have been identified as the primary target of leptin action in a seminal study demonstrating that AGRP neuron–specific Lepr deletion at the adult stage in mice causes severe hyperphagia, obesity, and diabetes." (PMID 36189793, 2022). "But outside of obesity, diabetes and the sequellae of metabolic disturbance, little is known about the impact of leptin on muscle homeostasis." (PMID 35844058, 2022).
Obesity (continued). "Leptin level increases in obesity due to enhanced adipose tissue secretion of adipokine and decreases when body weight is reduced." (PMID 35409072, 2022). "The fact that the sympathetic sensitivity of adipose tissue is reduced in obesity also contributes to explain the presence of increased leptin levels in the obese state, aside from the limited cases where leptin is absent." (PMID 34523036, 2022). "Elevated levels of circulating fatty acids in the setting of obesity and leptin resistance increase palmitoylation of proteins." (PMID 35119166, 2022). "Together with other adipokines, leptin is responsible for the inflammatory state found in obesity and with both direct and indirect effects that lead to type 2 diabetes, metabolic syndrome, and cardiovascular disease." (PMID 36213199, 2022). "Second, breast milk contains bioactive substances such as adiponectin, leptin and ghrelin, which can influence the proliferation and differentiation of the infant’s adipocytes, and have a protective effect against future obesity." (PMID 36457121, 2022). "Obesity leads to increased leptin levels and insulin resistance, and an experimental study indicated that leptin regulates the development of insulin resistance through its effects on the liver." (PMID 35941672, 2022). "The hormone leptin exerts its function in the brain to reduce food intake and increase energy expenditure to prevent obesity." (PMID 36131285, 2022). "Leptin is a pro-inflammatory product of the obesity gene, which is produced predominantly by differentiated white adipose tissue and acts in the brain to regulate energy homeostasis." (PMID 36235638, 2022). "Leptin, a hormone consistently related to obesity and obesity-related alterations, has been shown to exert direct and indirect effects on adipocyte metabolism." (PMID 35893926, 2022). "Several clinical studies have demonstrated alterations in leptin, visfatin and chemerin biosynthesis in obesity." (PMID 35549673, 2022). "Leptin is produced in the white adipose tissue and regulates energy homeostasis, spending, feed intake, reproduction, and obesity." (PMID 36428433, 2022). "In the next section, the main LEP and LEPR gene mutations associated with obesity and CRC are described to review their impact and potential link with obesity and CRC." (PMID 35563103, 2022). "Obesity usually leads to IR, Some studies have shown that altered secretion of cytokines in obesity such as TNF-α, IL-6, and leptin induce IR in obesity, while adiponectin stimulates insulin sensitivity." (PMID 36451420, 2022). "In this research, to find the correlation between cortisol and leptin secretory patterns in women with obesity, we keep the units for both hormones consistent." (PMID 35480480, 2022). "WP supplementation regardless of RE significantly alleviated hyperleptinemia by lowering fat mass as indicated by the normalized mRNA expression level of leptin in sarcopenic obesity." (PMID 36297085, 2022). "Leptin is an adipokine secreted by adipose tissue that increases in obesity and has central actions not only at the hypothalamic level but also in other regions and nuclei of the central nervous system (CNS) such as the cerebral cortex and hippocampus." (PMID 35563589, 2022). "The possible reason is that individuals with obesity, especially those with central obesity, tend to have higher TG and leptin levels." (PMID 36698957, 2022). "In obesity, the leptin resistance (increase level of leptin) is often observed, which is associated with disruption in production of cytokine, increased susceptibility to infectious and autoimmune diseases, and upregulated inflammatory responses." (PMID 36094704, 2022). "Obesity is considered one of the main environmental risk factors for CRC pathogenesis, with leptin being an important adipokine involved in both obesity and CRC." (PMID 35563103, 2022).
Obesity (continued). "In our study, diabetes status was balanced between EC and control patients, and only leptin differed among patients when stratified according to hypertension status or obesity." (PMID 36505829, 2022). "One such example of epigenetic change is suppression by poly unsaturated fatty acid of the leptin gene among the newborns of women with obesity which decreases the normal function of leptin, that increases satiety." (PMID 35391836, 2022). "In conclusion, our results demonstrate the difficulty in conclusively explaining human obesity in terms of the well-known LEP and LEPR genes." (PMID 35886710, 2022). "Studies have shown that central inhibition of the cellular inflammatory pathway in the hypothalamus can promote leptin and insulin sensitivity, reduce high fat food intake, and consequently protect against high fat food induced obesity." (PMID 35911732, 2022). "Leptin is a product of the obesity gene and plays a role in the regulation of food intake, lipolysis, and glucose homeostasis." (PMID 36619541, 2022). "This study’s purpose was to reveal the association of adipokines (leptin, adiponectin), hs-CRP, and IL-6 with well-known cardiovascular risk factors (lipid profile, diabetes control, obesity, physical activity) in children and adolescents with T1D." (PMID 36010052, 2022). "In fact, one study found that serum leptin was 318% higher in individuals with obesity compared to lean participants." (PMID 36313760, 2022). "Paradoxically, reducing leptin levels in mouse models of obesity improved metabolism, suggesting a new hormonal technique for combatting disease." (PMID 35269504, 2022). "Obesity is characterized by a decreased adiponectin/leptin ratio, which has been recently suggested as an estimator of dysfunctional adipose tissue." (PMID 35565781, 2022). "In the non-T2DM group with obesity, the level of leptin in the blood significantly correlated with the treatment response; the mean leptin level in the blood of responders (73.05 ng/ml) was lower than that in non responders (125.99 ng/ml; p = 0.018)." (PMID 35251693, 2022). "Leptin is the most secreted adipokine in white adipose tissue and it also seems to trigger obesity-related OA via Stat3." (PMID 35548357, 2022). "The regulation of paraventricular hypothalamic nuclei by leptin-controlled arcuate nucleus neuron terminals is strongly involved in the pathogenesis of obesity." (PMID 35388304, 2022). "Leptin contributes to the pathophysiology of obesity-related CRC by disrupting signaling pathways at the colon’s adipokine receptor." (PMID 36059323, 2022). "Mice with haploinsufficiency of Socs3 display greater leptin sensitivity than wild-type mice and are protected against the development of diet-induced obesity." (PMID 34523036, 2022). "The up regulation of SOCS3 in POMC neurons leads to the damage of STAT3 signal, resulting in leptin resistance and obesity." (PMID 36615730, 2022). "Leptin (LEP), the circulating product of the obesity gene, is a 16-kDa glycoprotein expressed and secreted primarily by the adipocyte." (PMID 35223490, 2022). "To date, the influence of leptin and leptin receptor expression and regulation has been centered around obesity." (PMID 35628271, 2022). "This was ascertained through our recently published work and other recent studies in which HFD-induced obesity in rats demonstrate a significantly higher leptin level and leptin resistance." (PMID 36364892, 2022). "In this review, we include two of the most common hormones, leptin and adiponectin, whose defective signaling in obesity can contribute to myocardial fibrosis." (PMID 35457013, 2022). "In particular, obesity and increased visceral fat are, in turn, perpetuating factors for DM2 in patients with OSA, causing leptin and insulin resistance." (PMID 35817418, 2022).